DICER1 (dicer 1, ribonuclease III)
Diseases named in the same sentence as DICER1 in open-access papers (continued):
Sharing a sentence is not in itself a finding about the gene and the disease.
thyroid nodule (18 papers, 2021 to 2026). A small circumscribed mass in the THYROID GLAND that can be of neoplastic growth or non-neoplastic abnormality. "Although thyroid nodules are common in the general population, they occur more frequently in children with DICER1 mutation." (PMID 40918549, 2025). "The additional study of one of the accompanying thyroid nodules (follicular nodular disease) confirmed the constitutional DICER1 variant, along with DICER1 p.(Asp1709Gly) and p.(Asp1810Val) variants." (PMID 40892116, 2025). "Eighty-seven percent of asymptomatic DICER1-mutated patients were shown to have thyroid nodules when an ultrasound was performed, and forty-three percent had lung cysts detected by CT scan." (PMID 40940982, 2025). "A small subset, approximately 1–2%, of thyroid nodules harbor early-driver mutations in the DICER1 gene, most of these nodules are benign, but some are clinically and histologically malignant." (PMID 41175860, 2025). "In a study conducted by Chong and colleagues, it was discovered that out of 14,993 fine-needle aspirations (FNA) of thyroid nodules, 214 (1.4%) revealed a DICER1 hotspot mutation." (PMID 38254836, 2024). "From the 17 patients with variants in the DICER1 gene, nine thyroid nodules had only one variant, while 8 showed 2 variants." (PMID 38330293, 2024). "The detection of 3p miRNAs associated with DICER1 mutations provides a promising path to enhance the diagnostic risk of malignancy in thyroid nodules." (PMID 36896180, 2023). "have reported that 84 % of thyroid nodules from 13 patients carrying germline DICER1 variations with MNG had somatic mutations in DICER1 hotspot amino acids." (PMID 34552563, 2021). "Khan and colleagues calculated the cumulative incidence of either MNG diagnosis or thyroidectomy (for MNG or thyroid nodules) in a family-based cohort study including 145 individuals with a germline DICER1 pathogenic variant and 135 family controls." (PMID 34170462, 2021). "Infarction has been recently described as a histologic feature of DICER1-mutated thyroid nodules." (PMID 41556091, 2026). "The upregulated set of 3p miRNAs in DICER1 tumors may be used as a diagnostic tool as they can serve as effective markers in distinguishing thyroid nodules with RNase IIIb variants." (PMID 40940982, 2025). "Moreover, while atrophic changes have not yet been described on the cytological level, there are reports suggesting that macrofollicular structures and papillary excrescences may also be detected in fine needle aspirates of DICER1-mutated thyroid nodules." (PMID 38637342, 2024). "In conclusion, we provide an overall mutational frequency of DICER1 and DGCR8 mutations in a bi-institutional cohort of thyroid nodules, showing that these mutations are rare events in FTs." (PMID 38252873, 2024). "When evaluating a thyroid nodule, the clinicians should pay special attention to any previous history as well as family history of DICER1-related neoplasms." (PMID 38254836, 2024). "Thyroid nodules with CNAs alone or in conjunction with lower risk mutations such as HRAS, NRAS, DICER1, EIF1AX, and GEA are more likely to be low-risk neoplasms." (PMID 36551633, 2022). "DICER1 is now recognized as a driver of pediatric and adult thyroid nodules." (PMID 38254836, 2024). "In fact, our analysis uncovered a clinically relevant miRNA signature in DICER1-mut malignant nodules that could help guide thyroid nodule diagnosis and management." (PMID 36896180, 2023). "Testing defined the unique molecular landscape of pediatric thyroid nodules (which, as opposed to adults, comprised more frequent gene fusions and DICER1 variants) and identified a sensitivity of 96% and specificity of 78% regarding cancer detection." (PMID 35679040, 2022).
ovarian tumors (17 papers, 2014 to 2025). "Herein, we present the case of a young Greek female patient with DICER1s, consisting of MNG and two sex-cord ovarian tumors, due to a novel pathogenic variant in the DICER1 gene." (PMID 40076617, 2025). "The International Ovarian and Testicular Stromal Tumor Registry (IOTSTR) reported that SLCT was one of the more common DICER1-associated neoplasms and the most common ovarian tumor overall in the DICER1 syndrome." (PMID 34599283, 2022). "Recently, hot-spot DICER1 mutations were found in ovarian tumors, and TARBP2 truncating mutations in tumor cell lines with microsatellite instability." (PMID 26087193, 2015). "Ovarian tumors are relatively rare in children and adolescent females, with mixed sex-cord-stromal tumors being a specific subtype that has a low incidence and is associated with DICER1 gene mutations." (PMID 40901169, 2025). "In the coming years, (international) data collection will hopefully provide information elucidating whether ultrasound surveillance of the ovaries reduces morbidity by facilitating earlier diagnosis and treatment of as yet asymptomatic individuals with DICER1-associated ovarian tumors." (PMID 34170462, 2021). "Sertoli-Leydig cell tumor (SLCT), a rare ovarian tumor that belongs to the group of sex cord stromal tumors, accounts for less than 0.5% of ovarian tumors, and is the second most frequent DICER1-related tumor after PPB." (PMID 35163487, 2022). "A copy number increase in Dicer1 and Ago2 loci has also been reported in, respectively, 24.8% and 51.5% of ovarian tumor regions." (PMID 34721577, 2021). "Although the level of penetrance of DICER1 mutations seems modest, mutational screening of DICER1 in children and young persons with MNG as well as rare tumors of the ovary, eyes, lungs or kidneys could still be useful." (PMID 24708902, 2014). "In actuality, DICER1 in nonepithelial ovarian tumors does not fit traditional tumor suppressor or oncogene models." (PMID 25676695, 2015). "Given the predominance of Dicer1 mutations in nonepithelial ovarian tumors, the appearance of epithelial HGSOC tumors arising from the fallopian tube stroma in the Dicer-Pten DKO mouse model might be likely due to the loss of Dicer1 function." (PMID 27602775, 2016).
prostate carcinoma (17 papers, 2010 to 2025). A carcinoma that arises from epithelial cells of the prostate gland. "Of the 32 TCGA tumors with germline DICER1 variation we analyzed, four (testicular, breast, and prostate cancers and melanoma) have been reported in cohorts with germline DICER1 pathogenic variation (DICER1‐carriers)." (PMID 30672147, 2019). "On the other hand, complete loss of Dicer1 leads to a collapse of gene expression regulation and DNA damage response, ultimately leading to cell death and inhibition of tumor development, as observed in models of lung cancer, sarcoma, retinoblastoma and prostate cancer." (PMID 41002430, 2025). "The data presented in this figure suggest that the expression of DNMT-1, PD1, Dicer1, and PD-L1 is markedly higher in prostate cancer patients compared to normal individuals and that their expression levels are positively correlated with the Gleason score." (PMID 40034825, 2025). "In the present study the expression of AGO2, SSB, and NF2 is downregulated in early-stage cancer and upregulated in advance-stage cancer; whereas PPARA was overexpressed and DICER1 was inhibited across all stages of prostate cancer." (PMID 31756185, 2019). "A growing body of evidence has indicated that the up- and downregulation of DICER1 are related to the development of tumorigeneses such as lung, breast, ovarian, skin, prostate cancers, and CRC via the alteration of miRNA expression." (PMID 30833603, 2019). "The prostate cancer data suggest a role for DICER1 as a tumour-suppressor gene, and we now report a patient with a DICER1 mutation who also suffers from a prolactinoma." (PMID 30306785, 2018). "However, there is also an observed increase in Dicer1 levels in the metastatic lesions in prostate cancer." (PMID 35237661, 2022). "By contrast, the strong majority of cancer types completely lacked DICER1 hotspot mutations, including some very commonly sequenced cancers (e.g., breast, pancreatic, and prostate cancers, each with >1000 cases)." (PMID 31417090, 2019). "Interestingly, in 5/9 genes (55.5%), i.e., ABHD2, DICER1, GSK3B, NR3C1, and NFIB mutations were localized to functional domains of their corresponding proteins, which suggest them to be highly critical genes for prostate cancers." (PMID 36468011, 2022). "In comparison, there were no obvious associations between the expression levels of ABHD2, FGF2, DCAF7, GSK3B, NACC2, DICER1, and FGFR1OP genes and survival rate in prostate cancer patients." (PMID 36468011, 2022). "The upstream regulators identified in advanced-stage prostate cancer in both PC3 and DU145 cells includes (i) AGO2, (ii) SSB, and (iii) neurofibromatosis 2 (NF2), and (iv) DICER1." (PMID 31756185, 2019). "The other genes showing molecular alterations in prostate cancer samples from highest to lowest are as follows; FGF2 (94/4990; 1.9%), NFIB (86/4990; 1.7%), CEP43 (62/4990; 1.2%), GSK3B (99/8961; 1.1%), DICER1 (101/8961; 1.1%), NR3C1 (53/4990; 1.1%) and ABHD2 (28/4,990; 0.6%)." (PMID 36468011, 2022). "However, the analysis of prostate cancer and CRC shows overexpression of DICER1 and other miRNA biogenesis genes in metastatic lesions." (PMID 26147304, 2015).
rhabdomyosarcoma (16 papers, 2013 to 2026). A rare aggressive malignant mesenchymal neoplasm arising from skeletal muscle. "Genetic testing of the rhabdomyosarcoma revealed a pathogenic c.4102dup (p.R1368fs) germline frameshift variant and a second c.5425G > A (p.G1809R) somatic missense variant in DICER1, as well as a somatic variant in BCOR." (PMID 42311827, 2026). "With this report, we advocate for further investigation of DICER1-associated rhabdomyosarcoma to improve management of this rare presentation." (PMID 42311827, 2026). "DICER1-associated ovarian and cervical embryonal rhabdomyosarcomas frequently exhibit cartilaginous differentiation, and her bladder tumor may be a related tumor." (PMID 31893257, 2018). "Another differential diagnosis, DICER1‐associated rhabdomyosarcoma, was excluded since no cases of intracranial DICER1‐associated rhabdomyosarcoma have been reported." (PMID 40040389, 2025). "In addition, this study identified 2 known DICER1-associated neoplasms (SLCT and rhabdomyosarcoma) in patients without any germline DICER1 variation, consistent with low-level mosaicism or tumor-only DICER1 variation." (PMID 33630087, 2021).
endometrial cancer (15 papers, 2012 to 2024). Primary or metastatic malignant neoplasm involving the endometrium (mucous membrane that lines the endometrial cavity). "In one investigation, they examined the cause of endometrial cancer stemness, focusing on the function of Dicer1 and the let-7 family." (PMID 38836981, 2024). "Modifications in the processing of miRNA have been linked to the development of endometrial cancer, while ovarian cancers are often accompanied by hotspot mutations in DICER1." (PMID 38836981, 2024). "Around 2% of endometrial cancers were found to have mutations in the Dicer1 hotspot region, according to recent research." (PMID 38836981, 2024). "The mechanism behind this tumor-predisposing phenotype was found to be that loss of Dicer1 resulted in aberrant let-7 family expression, and regulated stemness in endometrial cancer cells." (PMID 38836981, 2024). "This was in line with previously reported endometrial cancer samples showing the human DICER1 mutation from the TCGA (The Cancer Genome Atlas)." (PMID 38836981, 2024). "Our approach suggests a role for DICER1 in endometrial cancer, where six of the nine observed mutations cluster around two Mg2+ binding sites in the RNase IIIb domain." (PMID 24362839, 2014). "Finally, we exploit prevalent DICER1 RNase III hotspot mutations in endometrial cancer to identify targets of specific miRNAs that are derepressed in this setting." (PMID 31417090, 2019). "The myometrial invasion was similarly linked to lower DICER1 expression, higher FIGO-grade tumours, and endometrial cancer recurrence." (PMID 38836981, 2024). "DICER1 is an endoribonuclease in charge of miRNA synthesis, and a crucial gene acting as a cancer-driving factor in endometrial cancer." (PMID 38836981, 2024). "The physical location of the DICER1 coding gene overlaps with DICER1-AS1, and the methylated DICER1 was reported to be involved in endometrial carcinoma invasion." (PMID 34307152, 2021). "In general, apparent passenger mutations in DICER1 were enriched in hypermutated cases (mostly colorectal and esophageal cancers, and POLE subclass of endometrial cancers) in both TCGA and IMPACT cohorts." (PMID 31417090, 2019). "We observed that derepression of let-7 targets was the strongest GSEA signature obtained in DICER1 endometrial cancer, with known let-7 oncogene targets HMGA2 and IGFBP2 strongly deregulated." (PMID 31417090, 2019). "In another study involving endometrial cancer cell lines, miR-130b suppressed DICER1 expression and led to the deregulation of miR-200, together with some other EMT-related proteins." (PMID 27391066, 2016). "The expression of miR-130b is increased in hyperplastic endometrium and increases even further in endometrial cancer, which, along with DICER1 dysfunction, leads to tumor aggression both in vitro and in vivo." (PMID 25637514, 2015). "We compared the expression of miR-130b and DICER1 between endometrial cancers and normal endometrium." (PMID 23680357, 2013). "qRT-PCR analysis indicated that miR-130b was lower in normal endometrium than in endometrial cancer while DICER1 was higher in normal endometrium than in endometrial cancer." (PMID 23680357, 2013). "Dicer1 dysregulations in epithelial cancers like ovarian and endometrial carcinomas are not as common as in nonepithelial cancers." (PMID 27602775, 2016). "Here we presented for the first time a comprehensive analysis of miR-130 family and DICER1 expression in endometrial cancer tissues, compared with normal endometrium." (PMID 23680357, 2013). "Since few DICER1 mutants lack multiple cases in individual tumor types, besides endometrial cancer, this approach could not be utilized broadly." (PMID 31417090, 2019).
Infertility (15 papers, 2011 to 2026). "Sertoli cell‐specific deletion of Dicer1 caused apoptosis of Sertoli cells after birth leading to degenerated testes, defective prepubertal spermatogenesis, and infertility." (PMID 30151880, 2019). "A side-by-side testes knockout experiment showed that Dicer1 and Drosha were each essential for spermatogenesis, since their deletion caused infertility." (PMID 28906477, 2017). "Early postnatal germ cell-specific loss of Dicer1 resulted in spermatogenic failure and infertility associated with down-regulation of testis miRNAs, deregulation of the testis transcriptome and preferential overexpression of sex chromosome genes." (PMID 23056286, 2012). "Hayashi and colleagues found that germ cell-specific deletion of Dicer1 causes a defect in proliferation of male gonocytes and late adult infertility, likely due to spermatogenic arrest." (PMID 21998645, 2011). "Recent studies have shown that the deletion of factors such as PGC and Dicer1 leads to blocked germ cell development in mice, resulting in a significantly lower number of germ cells than in wild-type or heterozygous mice, ultimately causing infertility." (PMID 41302865, 2025). "In the mouse model, the deficiency of the miRNA processing enzyme Dicer1 led to luteal insufficiency and infertility in female mice, with further studies showing that the observed impaired luteal angiogenesis was partly caused by the deletion of miR-17-5p and let-7b." (PMID 36226169, 2022). "Dicer1 knockout oocytes also led to the loss of oocyte meiotic spindle structure and chromosome condensation, in turn, resulting in the loss of meiotic division follicular developmental abnormalities, ovulation disorders, apoptosis and infertility." (PMID 24959893, 2014). "Here, we investigate the loss of Dicer1 in mouse postnatal male germ cells to determine how disruptions in the miRNA biogenesis pathway may contribute to infertility." (PMID 23056286, 2012). "We have earlier shown that deletion of Dicer1 in early spermatogenic cells mainly affects haploid male germ cell differentiation, causing major defects in chromatin condensation and nuclear shaping of spermatids, which leads to severe oligoasthenoteratozoospermia and infertility." (PMID 32484548, 2020). "Therefore, deleting Dicer1 in early postnatal germ cells resulted in deregulation of transcripts encoded by genes on the sex chromosomes, impaired meiotic progression and led to spermatogenic failure and infertility." (PMID 23056286, 2012). "Knockout of the key miRNA maturation gene DICER1 in germ cells disrupts spermatogenesis, resulting in infertility." (PMID 41546098, 2026). "Dicer1 conditional knockouts (cKOs) in mouse oocytes lead to severe effects such as infertility, abnormal chromosomal alignment, and disrupted spindle organization." (PMID 28906477, 2017). "Dicer1 d/d ovaries transplanted into the wild-type female mouse led to infertility, but transplantation of wild-type mouse ovary into Dicer1d/d females resulted in offspring, suggesting that this fertility defect was derived from the ovary." (PMID 24959893, 2014). "We have previously shown that the spermatogonia-specific deletion of Dicer1, using Cre under the control of the Ddx4 promoter, leads to infertility." (PMID 25244517, 2014). "The present study aims to further characterize the molecular mechanisms that lead to massive apoptosis, spermatogenic failure and infertility following Dicer1 inactivation in male germ cells." (PMID 25244517, 2014). "Deletion of Dicer1 in type A spermatogonia by Neurog3 promoter-driven cre (Ngn3-cre) resulted in defective spermatogenesis and infertility characterized by the arrest of spermatid elongation prior to the histone-protamine exchange." (PMID 23056286, 2012). "If endo-siRNAs were principally responsible for the Dicer1 infertility phenotype, then Drosha KO males should have been fertile because levels of endo-siRNAs were unchanged." (PMID 23056286, 2012).
Infertility (continued). "We show that the selective ablation of Dicer1 at the early onset of male germ cell development leads to infertility, due to multiple cumulative defects at the meiotic and post-meiotic stages culminating with the absence of functional spermatozoa." (PMID 21998645, 2011). "Inactivating Dicer1 in female rats led to atypical follicles formation and infertility." (PMID 36564840, 2022). "Interestingly, the ablation of either Dicer1 or Dgcr8 in the germ cell lineage using the Ddx4:Cre transgene led to complete infertility." (PMID 25244517, 2014). "Similarly to the Dicer1 mutant, ablation of Drosha in the male germ line results in complete infertility characterized by impaired spermatogenesis, and depletion of spermatocytes and spermatids, leading to oligozoospermia and azoospermia." (PMID 25244517, 2014). "The fact that fertility was not rescued in the Drosha KO mice suggests that broad-based reduction in the levels of miRNAs in our model may better explain the Dicer1 knockout infertility phenotype." (PMID 23056286, 2012). "Therefore, by deleting Dicer1 from male germ cells, endo-siRNA levels may also be reduced and thus confound the etiology of the Stra8-icre;Dicer infertility phenotype." (PMID 23056286, 2012). "Selective ablation of Dicer1 in Sertoli cells leads to infertility, due to the complete absence of spermatozoa." (PMID 21998645, 2011). "Our results indicate that Dicer1 is required for normal spermatogenesis, since the deletion of Dicer1 in male germ cells led to multiple defects in meiosis and spermiogenesis resulting in the absence of functional spermatozoa and complete infertility." (PMID 21998645, 2011).